PLIN1 (perilipin 1)
Diseases named in the same sentence as PLIN1 in open-access papers (continued):
Sharing a sentence is not in itself a finding about the gene and the disease.
lymphedema (1 paper, 2024). Excess fluid collection in tissues, causing swelling. "Interestingly, the correlation of expression profiles of perilipin (PLIN)-1 and -3 and podoplanin (PDPN) has been hypothesized as a potential link between lymphangiogenesis and lipolysis, but has not yet been explored in the context of lymphedema." (PMID 38612716, 2024).
MODY (1 paper, 2018). "We initially tested 1323 patients with a clinical suspicion of MODY of which four had a heterozygous null variant in PLIN1 (probands 1 to 4)." (PMID 30020498, 2018).
odontogenic tumor (1 paper, 2025). "Increased perilipin-1 and perilipin-2 (also known as adipophilin) expression has been linked to EMT, a key process in odontogenic tumor invasion." (PMID 40699660, 2025).
ovarian carcinoma (1 paper, 2021). A malignant neoplasm originating from the surface ovarian epithelium. "Subsequently, the remaining prognostic biomarkers from other cancer types were also assessed by OSov, which demonstrated that these genes (SFRP4, NUAK1, MFAP2, PLIN1 and EFNB2) exhibited good performance in predicting ovarian cancer patient outcome." (PMID 35053021, 2021).
prostate carcinoma (1 paper, 2023). A carcinoma that arises from epithelial cells of the prostate gland. "Many of the immune response related (e.g., IRF8, JAK3, PTGER4, RELB, IFITM3) and part of the lipid metabolism related genes (e.g., NR1H4, PPARGC1B, PLIN1, HSD17B14) were identified to be adaptive which addressed their significance for prostate cancer." (PMID 36809527, 2023).
soft tissue sarcoma (1 paper, 2023). A malignant neoplasm arising from muscle tissue, adipose tissue, blood vessels, fibrous tissue, or other supportive tissues excluding the bones. "The results showed the potential of PLIN1 as a useful diagnostic marker in the pathological reading of soft tissue sarcomas." (PMID 37998612, 2023).
tumor (38 papers, 2015 to 2025). "A receiver operating characteristic (ROC) curve was also generated to explore whether PLIN1 is a good diagnostic marker for discriminating tumor tissues from normal tissues." (PMID 27359054, 2016). "Heatmap analysis showed marked upregulation of PLIN3, whereas LIPG, DGAT2, CIDEC, and PLIN1 were down-regulated in tumor tissues and GbPDTOs compared to those in normal tissues." (PMID 41376821, 2025). "PLIN1 is involved in lipid metabolism modulation in tumor microenvironment and is correlated with tumor development as well as metastasis." (PMID 39870645, 2025). "Among these candidate genes, we noticed PLIN1, which is recognized as a tumor suppressor in a variety of malignancies." (PMID 39870645, 2025). "Key genes, including CD36, FABP4, PLIN1, PLIN4, SCD5, and ACSLs, were consistently downregulated in tumor tissues, with further reductions observed in KRAS-mutated samples." (PMID 40860798, 2025). "Among them, the mRNA expression level of PLIN1 gradually decreased with the increase in tumor grade, while PLIN2 showcased an increasing trend." (PMID 37189627, 2023). "Several of the most highly induced genes, CHI3L1, GPX1, PLIN1, PLIN4, and JAK3, have been linked to enhanced growth or cell survival in other tumor types." (PMID 35787784, 2022). "The levels of Lipe, a regulator of lipolysis, as well as of Plin1 and Srebf1, involved in the control of lipid metabolism, were unchanged in the tumor hosts." (PMID 35392166, 2022). "Of note, the UCSC predicted that HDAC2 was a potential transcriptional regulator of PLIN1, an identified tumor suppressor in BC progression." (PMID 32110804, 2020). "In nerves isolated from mice 14 days after E0771 tumor cell injection adipocytes are partly shrunken or perilipin-1 was distributed throughout the cells." (PMID 32013137, 2020). "In order to measure ObR, AdipoR1, adiponectin and perilipin 1 levels and localization in both tissue samples, we performed immunohistochemistry assays on adipose tissue explants from normal (hRAN) and tumor (hRAT) kidney." (PMID 31534630, 2019). "Indeed, large Perilipin-1-positive non-tumor areas were apparent in LTX treated tumors, whereas the the non-treated control tumors were dominated by tumor tissue with minimal Perilipin-1 positive non-tumor areas." (PMID 40097378, 2025). "And PLIN1 overexpression notably suppressed tumor growth in vivo." (PMID 39870645, 2025). "PLIN1 is recognized as a tumor suppressing gene in multiple malignancies, such as HCC." (PMID 39870645, 2025). "PLIN1 belongs to the PLIN family that involved in tumor lipid metabolism modulation." (PMID 39870645, 2025). "In breast cancer, PLIN1 is identified as a tumor suppressor, which is lowly expressed and may act as marker or therapeutic target." (PMID 39870645, 2025). "The expression of PLIN1 was exhibited in the cytoplasm of the tumor cells." (PMID 37998612, 2023). "This also indicates that the expression of PLIN1 is affected by the tumor microenvironment." (PMID 37998612, 2023). "PLIN1 was also expressed in inflammatory cells in the stroma surrounding tumor cells." (PMID 37998612, 2023). "And PLIN1, a recently identified anti-tumor gene in BC was chosen to be research object since UCSC suggested that HDAC2 might be one of potential regulators of it." (PMID 32110804, 2020). "In addition, in the present work, we found that adipocytes from tumor microenvironment express diminished levels of perilipin-1." (PMID 31534630, 2019). "Additionally, within the tumour region, tumour cells were positive for PLIN-1, which could represent the transfer of lipids from adipocytes to tumour cells." (PMID 40447655, 2025). "Specifically, CD36, FABP4, PLIN1, SCD5 and ACSL4 were significantly downregulated in tumor samples (p < 0.05)." (PMID 40860798, 2025).
tumor (continued). "We determined mRNA expression profiles of PLIN1, PLIN2, PLIN3, PLIN4, and PLIN5 in a panel of OC cell lines and tumor tissue, using RT‐PCR." (PMID 41041279, 2025). "Specifically, we observed a significant down-regulation of some of the most relevant genes in the PPAR pathway (CD36, FABP4, PLIN1, PLIN4, SCD5 and ACSL4) in tumor tissue samples." (PMID 40860798, 2025). "A significant down-regulation of CD36, FABP4, PLIN1, SCD5 and ACSL4 in tumor samples has also been validated by RT-qPCR." (PMID 40860798, 2025). "Decreased levels of Plin1 were seen in wild-type OH-BBN exposed animals and MB49 day 5 orthotopic tumor bearing animals when compared to healthy controls of respective model." (PMID 34232958, 2021). "The expression of PLIN1 (p < 0.001), FABP4 (p = 0.029), CPT-1A (p = 0.001), ACOX-1 (p < 0.001), and FASN (p < 0.001) differed significantly among these tumor subtypes." (PMID 25751270, 2015). "Additionally, MDL800 abolished phosphorylation of perilipin 1 and HSL, expression of ATGL and cAMP production, demonstrating the complete inhibition of tumour‐induced lipolysis." (PMID 39971710, 2025). "The correlation between tumor stage < 2 and ≥2 and PLIN1 expression was also not statistically significant with a p value of 0.455." (PMID 37998612, 2023). "On the other side of the volcanos, PLIN1 is one of top down-regulated genes in both our Tumor-vs-Normal and Tumor-vs-Adjacent DEGs lists." (PMID 29268695, 2017). "When comparing expressions of lipid metabolism—related proteins among molecular subtypes, the expression of PLIN1 (p < 0.001), FABP4 (p = 0.029), CPT-1A (p = 0.001), ACOX-1 (p < 0.001), and FASN (p < 0.001) differed significantly among the different tumor subtypes." (PMID 25751270, 2015). "Results showed that some of the most relevant pathway’s regulators and effectors (CD36, FABP4, PLIN1, PLIN4, SCD5 and ACSL6) showed significantly lower expression in tumor tissue samples (p.adjusted < 0.01, data not shown)." (PMID 40860798, 2025). "The results demonstrated that the mRNA levels of PLIN1/PLIN4/PLIN5 were not correlated with tumor recurrence status, while PLIN2 and PLIN3 were correlated with tumor recurrence status." (PMID 37189627, 2023). "Although we witnessed blunted reductions when compared with sham animals in genes such as Lipe, Plin1, Pnpla2, and Fasn in tumour mice treated with ACVR2B/Fc compared untreated tumour mice, there were not statistically significant differences between the two tumour groups." (PMID 33200567, 2020).
cancer (21 papers, 2016 to 2025). A tumor composed of atypical neoplastic, often pleomorphic cells that invade other tissues. "Dysregulation of lipid metabolism is a notable feature of various cancers, and PLIN1 expression has been linked to disease outcomes in multiple cancers." (PMID 40041860, 2025). "Our results show, for the first time, profound changes in ATGL and perilipin-1 protein expression in the subcutaneous white adipose tissue of cachectic cancer patients." (PMID 28830524, 2017). "We further generated several Kaplan-Meier analysis curves based on the cBioPortal database for 8 cancers types, in which low PLIN1 expression correlated with PLIN1 deletion, as detailed above." (PMID 27359054, 2016). "The results revealed that PLIN1 expression is shallow deleted in 21 human cancer types, of which 14 exhibited deletion of PLIN1 in more than 15% (66.7%, 14/21) of cases, 7 exhibited deletion in more than 20% (33.3%, 7/21) of cases and 3 exhibited deletion in more than 30% (14.3%, 3/21) of cases." (PMID 27359054, 2016). "The high-throughput proteomics analysis revealed differential expressions of Acsl1, Plin1, Dbil5, Plin4, Col12a1, Col1a1, Col5a3, Col1a2, and Dcn, which are associated with the PPAR signaling pathway, protein digestion and absorption, and the protein glycan pathway in cancer." (PMID 36874004, 2023). "We next analyzed the Western blot results of CGI-58, PLIN1, and PLIN5 according to cancer type (colorectal, n = 6; gastric, n = 5; pancreatic, n = 7) vs controls (n = 8)." (PMID 38167536, 2024). "The comparison of proteins interacting with PLIN1 in adipocytes with those interacting with PLIN2 and ATGL in two cancer cell lines provides insight into the core components of LDs." (PMID 38130664, 2023). "ACSL3, AIFM2, HSD17B7, LPCAT1, LSS, PLIN3 and RAB10 were up-regulated with the progression of cancer stage of HCC patients, while CIDEB, G0S2, HSD17B13, PLIN1 and PLIN2 were down-regulated." (PMID 37464334, 2023). "They suggested that PLIN1, PLIN2, and PLIN3 may be involved in cancers such as hepatocellular adenoma and carcinoma, sebaceous adenoma and carcinoma, and lipoma tumors, while PLIN5 was excluded as not sufficient proof was given." (PMID 34067931, 2021).
metabolic disease (11 papers, 2017 to 2025). A congenital disorder (due to inherited enzyme abnormality) or acquired (due to failure of a metabolically important organ) disorder resulting from an abnormal metabolic process. "There is only limited data on the relationship between PLIN1, adipose tissue endocrine function, and metabolic disorders." (PMID 35886029, 2022). "The finding that CpG methylation controls the activity of the PLIN1 promoter thus shed new light on the regulation of adipocyte lipolysis and potentially why lipolysis is altered in metabolic diseases." (PMID 28860604, 2017). "In particular, mutations in PLIN1 and PLIN4 have been linked to many metabolic phenotypes, and loss-of-function heterozygous mutations in PLIN1 and PLIN4 positively and negatively, respectively, correlate with metabolic disease." (PMID 39297796, 2024). "We tested this approach with metabolic disease genes expressed in adipocytes, identifying and subsequently validating novel interactions between BSCL2 and PLIN1 (protein–protein) as well as CEBPA and AGPAT2 (genetic regulatory)." (PMID 30940487, 2019).
infection (3 papers, 2018 to 2024). The state of being infected such as from the introduction of a foreign agent such as serum, vaccine, antigenic substance or organism. "During infection of promyelocytic cells, A. phagocytophilum increases expression of perilipin 1 (PLIN1), the major host protein important for regulation of LD formation and lipolysis, suggesting a possible role of host LDs as a source of cholesterol and fatty acids." (PMID 32731350, 2020). "qRT‐PCR analysis revealed that lenti‐shPPARGC1B infection significantly decreased PPARGC1B mRNA expression, which resulted in significant down‐regulation of the mRNA levels of the adipogenic differentiation markers (PPARγ, PLIN1, LPL and FABP4) as compared with the lenti‐ctrl infection." (PMID 29993187, 2018). "qRT‐PCR analysis revealed that lenti‐shZFP36L1 infection remarkably decreased ZFP36L1 mRNA expression which resulted in significant up‐regulation of the mRNA levels of the adipogenic differentiation markers (PPARγ, PLIN1, LPL and FABP4) as compared with the lenti‐control (lenti‐ctrl) infection." (PMID 29993187, 2018).
bacterial infection (2 papers, 2024). "PLIN1 can respond to IMD activation and alter morphological changes in LDs to mitigate the immune response against bacterial infections in Drosophila." (PMID 38690912, 2024).
cardiovascular disease (2 papers, 2022). "In contrast to the originally reported monogenic lipodystrophy syndrome, PLIN1 haploinsufficiency causes a favorable metabolic profile and may protect against cardiovascular disease." (PMID 35235652, 2022). "Our study suggests that PLIN1 haploinsufficiency causes a favorable metabolic profile and may protect against cardiovascular disease." (PMID 35235652, 2022). "Our results suggest that PLIN1 PTVs may cause some reduction in risk of cardiovascular disease and blood pressure." (PMID 35235652, 2022). "Phenotypic follow-up suggests that LoF of PLIN1, PDE3B, and ACVR1C favorably affects metabolic phenotypes (eg, triglycerides [TGs] and high-density lipoprotein [HDL] cholesterol concentrations) and reduces the risk of cardiovascular disease, whereas PLIN4 LoF has adverse health consequences." (PMID 34875679, 2022). "The possible underlying mechanism of lower cardiovascular disease seen in individuals with PLIN1 PTVs is not known but it could be secondary to lower blood pressure in combination with a favorable lipid profile seen in these individuals." (PMID 35235652, 2022).
degenerative diseases (1 paper, 2025). "IF regulates lipid metabolism primarily via genes including FABP4, WNT10B, PCK1, PLIN1, LEPR, and ADIPOQ, providing energy for cold adaptation, whereas PF positively influences in vivo degenerative diseases mainly through genes such as ATP5F1A, ATP5PO, SDHB, NDUFS8, SDHA, and COX5A." (PMID 40136641, 2025).
PLIN1 also shares sentences with these, for which no sentence is quoted: Glucose intolerance (5 papers); hypertriglyceridemia (5); ameloblastoma (2); Cachexia (2); Dunnigan syndrome (2); sarcoma (2); Sepsis (2); acne vulgaris (1); ameloblastic carcinoma (1); angiolipoma (1); Atypical progeroid syndrome (1); Berardinelli-Seip congenital lipodystrophy type 2 (1); bladder urothelial carcinoma (1); bone metastasis (1); cervical cancer (1); cervical squamous cell carcinoma (1); chronic hepatitis B (1); Cirrhosis (1); clear cell renal cell carcinoma (1); colitis (1); colon adenocarcinoma (1); coronary artery disease (1); dysplasia (1); endocrine disorders (1); esophageal carcinoma (1); Ewing sarcoma (1); familial partial lipodystrophy type 4 (1); fibrosarcoma (1); Gaucher disease (1); glioblastoma (1).
A further 30 diseases each share a sentence with PLIN1 in 1 paper.